TMEM134 (transmembrane protein 134)
Synonyms: FLJ21749
Tractability: Antibody: UniProt predicts a signal peptide or a membrane-spanning region.
Gene: Protein-coding gene on chromosome 11 (67,461,710 to 67,469,288, reverse strand). Ensembl gene ENSG00000172663.
Subcellular location: Membrane; Cytoplasm, perinuclear region
Subcellular location (Human Protein Atlas): Cytosol
Gene Ontology:
Molecular function: protein binding
Cellular component: cytosol; perinuclear region of cytoplasm; membrane
Genetic constraint (gnomAD): Loss-of-function variants: 36 observed, 21.33 expected, observed/expected ratio (o/e) 1.69, 90% interval 1.27 to 1.95. The synonymous counts are far from expectation, so gnomAD's model fits this gene poorly and the ratio says little. Missense variants: 339 observed, 221.03 expected, observed/expected ratio (o/e) 1.53, 90% interval 1.4 to 1.68. Synonymous variants: 133 observed, 88.71 expected, observed/expected ratio (o/e) 1.5, 90% interval 1.3 to 1.73.
Homologues: Orthologues: chimpanzee TMEM134 (100% identical), pig TMEM134 (95% identical), mouse Tmem134 (93% identical), guinea pig TMEM134 (92% identical), rat Tmem134 (92% identical), dog TMEM134 (88% identical), macaque TMEM134 (77% identical), zebrafish tmem134 (54% identical), Drosophila melanogaster CG12025 (27% identical), Caenorhabditis elegans F21F3.7 (23% identical).
Diseases named in the same sentence as TMEM134 in open-access papers:
TMEM134 is named in the same sentence as 5 diseases in open-access papers, as found by Europe PMC text mining. Sharing a sentence is not in itself a finding about the gene and the disease. The quoted sentences say what the papers report.
Obesity (3 papers, 2017 to 2025). Accumulation of substantial excess body fat. "Downregulation of monocyte IMPDH2 (β = −0.496, p = 0.004) and TMEM134 (β = −0.314, p = 0.043) was associated with obesity in adults (BMI >30 kg/m2), paralleling our findings in children." (PMID 29203885, 2017). "In summary, monocyte TMEM134 downregulation is observed in childhood obesity, associated with obesity in adults at risk, and correlates with a higher SYNTAX score in adults at risk in an obesity-dependent fashion." (PMID 29203885, 2017). "Our study showed a distinctive monocyte gene expression profile in childhood obesity, and downregulation of monocyte IMPDH2 and TMEM134 was also associated with obesity in the adult cohort at risk." (PMID 29203885, 2017). "Especially the role of TMEM134 in monocytes gains traction, as downregulation of monocyte TMEM134 was associated with obesity in children and adults, and coincided with a higher SYNTAX atherosclerosis score in adults at risk for ischemic cardiovascular disease." (PMID 29203885, 2017). "However, the present study pinpoints Tmem134, a protein located in the perinuclear region of the cytoplasm, involved in RNA splicing and associated with obesity, as the best target for the gene therapy of IESS in rats of both sexes based on symmetrical expression change in both sexes." (PMID 40699779, 2025). "Hence TMEM134 downregulation in childhood obesity and adults with cardiovascular risk may reflect obesity-induced CD14++CD16- and CD14++CD16+ monocytosis." (PMID 29203885, 2017). "The identified potential candidate gene TMEM134 influences obesity and atherosclerosis in adults." (PMID 31665138, 2019).
atherosclerosis (2 papers, 2017 to 2019). A disease characterized by the build-up of fatty material and calcium deposition in the arterial wall resulting in partial or complete occlusion of the arterial lumen. "Moreover, downregulation of monocyte TMEM134 was associated with a higher SYNTAX atherosclerosis score in adults." (PMID 29203885, 2017).
leukemia (1 paper, 2023). A malignant (clonal) hematologic disorder, involving hematopoietic stem cells and characterized by the presence of primitive or atypical myeloid or lymphoid cells in the bone marrow and the blood. "This emphasizes the critical roles of RNA splicing, including a novel tumor specific alternative splicing event in Tmem134, in the emergence and maintenance of leukemia." (PMID 37130348, 2023). "Then, we tested the in vivo effects of TMEM134 exon 6 skipping on leukemia maintenance by transplanting leukemic cells harboring TMEM134α or TMEM134β into recipient mice." (PMID 37130348, 2023). "In addition, we used 2 different strategies by abrogating the splicing site of exon 6 (sgExon6) or deleting the whole exon 6 (sgIntron5 combined with sgIntron6) for enforced exon 6 skipping of Tmem134 in leukemia cells." (PMID 37130348, 2023). "Furthermore, we introduced synonymous mutated TMEM134α/β cDNA into the THP-1 and HL-60 cell line (2 kinds of human leukemia cell lines) with endogenous TMEM134 knockout." (PMID 37130348, 2023).
cancer (1 paper, 2023). A tumor composed of atypical neoplastic, often pleomorphic cells that invade other tissues. "Furthermore, we also measured the PSI values of TMEM134 exon 6 skipping in multiple cancers and found that it happens in the most of them more or less, suggesting that it may have the general function in pan-cancer." (PMID 37130348, 2023).
tumor (1 paper, 2023). "Thus, exon 6 skipping of TMEM134, which likely abrogated the tumor suppression function of full-length TMEM134, drove aggressiveness in AML." (PMID 37130348, 2023).